EHMT1 (euchromatic histone lysine methyltransferase 1)
Diseases named in the same sentence as EHMT1 in open-access papers (continued):
Sharing a sentence is not in itself a finding about the gene and the disease.
lung carcinoma (continued). "Thus, we suggest that the function of EHMT1 is deeply related to the process of cell apoptosis and cell cycle in the development of lung cancer." (PMID 34214254, 2021). "Here, we demonstrate the involvement of EHMT1, a histone lysine methyltransferase, in lung cancer." (PMID 34214254, 2021). "In addition, we observed growth suppression in lung cancer cell lines upon knockdown of EHMT1 via FACS analysis of Annexin V staining and caspase‐3/7 activity." (PMID 34214254, 2021). "In addition, to verify the overexpression of EHMT1 in lung cancer, we performed immunohistochemical analysis with a tissue microarray of lung cancer and normal lung tissues." (PMID 34214254, 2021). "Collectively, our findings indicate that dysregulation of EHMT1 may play an important role in the process of lung cancer cell growth, and suggest that EHMT1 may be a rational drug target in the treatment of lung cancer." (PMID 34214254, 2021). "Our findings suggest that EHMT1 may potentially serve as a therapeutic target for the treatment of patients with lung cancer." (PMID 34214254, 2021). "We hypothesized that EHMT1 plays an important role in lung cancer proliferation and could be a therapeutic target for lung cancer." (PMID 34214254, 2021). "However, patient‐derived lung cancer organoids are more effective than 3D spheroid systems for estimating the clinical effect of EHMT1 expression in lung cancer patients because cancer organoids more accurately resemble cancer cells and the tumor environment." (PMID 34214254, 2021). "Thus, we suggest that downregulation of CDKN1A expression by epigenetic regulation of EHMT1 plays an important role in lung cancer proliferation." (PMID 34214254, 2021). "Thus, we established the hypothesis that induction of CDKN1A expression by EHMT1 knockdown induces cell cycle arrest and apoptosis in lung cancer cells." (PMID 34214254, 2021). "In this study, we constructed 3D spheroid models with lung cancer cell lines using an ultra‐low‐attachment (ULA) plate system and assessed spheroid formation and target interactions with an EHMT1 knockdown model." (PMID 34214254, 2021). "EHMT1's expression in prostate cancer has not been studied; however, it is overexpressed in lung cancer and cells that underwent EHMT1 knockdown-induced apoptosis and G1 cell cycle arrest." (PMID 38173042, 2024). "Additionally, euchromatic histone lysine methyltransferase 1(EHMT1) downregulation of CDKN1A expression plays a crucial role in lung cancer proliferation, indicating the potential for further research on EHMT1 in lung cancer drug resistance." (PMID 38525426, 2024). "Metformin suppressed the protein and mRNA expressions of euchromatic histone lysine methyltransferase 1, 2 (EHMT1, EHMT2), enhancer of zeste 1, 2 polycomb repressive complex 2 subunit (EZH1, EZH2), lysine methyltransferase 2A, 2B (MLL1, MLL2), and WD repeat domain 82 (WDR82) in lung cancer cells." (PMID 33578894, 2021).
microcephaly (5 papers, 2017 to 2024). A congenital or acquired developmental disorder in which the circumference of the head is smaller than normal for the person's age and sex. "In case 21, a 2-year-old girl with microcephaly, psychomotor delay, hypotonia, seizures, brachydactyly, behavioral and sleep disturbances, a de novo heterozygous variant of EHMT1, was detected." (PMID 33337535, 2021). "Interestingly, no brain volume abnormalities are described in animal models of EHMT1 haploinsufficiency whereas microcephaly was found in 20% of patients carrying intragenic EHMT1 mutations." (PMID 33263776, 2021).
prostate carcinoma (5 papers, 2017 to 2024). A carcinoma that arises from epithelial cells of the prostate gland. "One study suggests that EHMT1 protein stabilization in SPOP mutation prostate cancer leads to increased DNA methylation." (PMID 37663929, 2023). "Considering that EHMTs are part of the REST complex responsible for repressing neuronal genes, we further investigated whether EHMT1/2-regulated genes were associated with NE transformation in prostate cancer." (PMID 37663929, 2023). "Furthermore, we investigated whether EHMT1/2 expression is associated with the aggressiveness of prostate cancer tumors." (PMID 37663929, 2023). "This study has identified lysine 450 and 451 methylations as novel posttranslational modifications of EHMT1 and demonstrated the functional importance of dual-lysine demethylation as a molecular switch in reprogramming EHMT1 activity in prostate cancer cells." (PMID 37663929, 2023). "In-depth analysis of posttranslational modifications of EHMT1 protein revealed the presence of methylation at lysine 450 and 451 residues in multiple prostate cancer models." (PMID 37663929, 2023). "Overall, these findings indicate that the dual-lysine demethylation of EHMT1 can expand its chromatin recruitment, activate oncogenic transcription programs, and promote prostate cancer cell proliferation and migration." (PMID 37663929, 2023). "To investigate the functional implications of K450/K451 methylation in prostate cancer cells, we generated three additional LNCaP stable cell lines expressing doxycycline-regulated V5-tagged EHMT1-K450R, K451R, or K450/451R mutants." (PMID 37663929, 2023). "The expression levels of EHMT1- or EHMT2-activated genes were significantly increased in CRPC compared with primary prostate cancer and normal prostate samples." (PMID 37663929, 2023). "Analysis of public prostate cancer datasets revealed that the EHMT1 gene is altered in 1.6% of primary prostate cancer samples, and the alteration rate is increased to 7% in CRPC, with the majority being gene amplification." (PMID 37663929, 2023). "Silencing EHMT1/2 or targeting their enzymatic activity with small-molecule inhibitors can markedly decrease prostate cancer cell proliferation and metastasis in vitro and in vivo." (PMID 37663929, 2023). "In summary, our study demonstrates the role of a novel EHMT1 modification as a biochemical switch in mediating its molecular activity and tumor-promoting function in prostate cancer." (PMID 37663929, 2023). "Moreover, we propose that the dual-lysine demethylation of EHMT1 acts as a critical molecular switch, triggering the induction of oncogenic transcriptional reprogramming in prostate cancer cells." (PMID 37663929, 2023). "Strikingly, concurrent demethylation of both lysine residues resulted in a rapid and profound expansion of EHMT1’s chromatin binding capacity, enabling EHMT1 to reprogram the transcription networks in prostate cancer cells and activate oncogenic signaling pathways." (PMID 37663929, 2023). "Importantly, the enhanced cell proliferation or migration observed in the K450/451R mutant was blocked by EHMT1 inhibition, suggesting that catalytic activity of EHMT1 is required for the unmethylated form to promote prostate cancer progression." (PMID 37663929, 2023). "Mechanistically, the chromatin binding of EHMT1 is significantly expanded through demethylation of both lysine 450 and 451 residues, which can serve as a critical molecular switch to induce oncogenic transcriptional reprogramming in prostate cancer cells." (PMID 37663929, 2023). "Furthermore, we examined the levels of this novel activation activity of EHMT1/2 in prostate cancer patient samples." (PMID 37663929, 2023). "Consistently, EHMT1 expression is significantly increased in CRPC compared with primary prostate cancer and normal prostate samples, suggesting that EHMT1 may function to promote the progression of CRPC." (PMID 37663929, 2023).
prostate carcinoma (continued). "The growth of these prostate cancer cells was reduced upon knockdown of either EHMT1 or EHMT2." (PMID 37663929, 2023). "UNC0642 markedly decreased the metastatic capability of PC-3 cells in vivo, indicating that targeting EHMT1/2 may prevent prostate cancer progression and metastasis." (PMID 37663929, 2023). "Recent studies have implicated EHMT1 and EHMT2 as critical epigenetic drivers in prostate cancer." (PMID 37663929, 2023). "Consequently, EHMT1 transcriptionally activated oncogenic programs, promoting prostate cancer development." (PMID 37663929, 2023). "However, data from us and others suggest that EHMT1/LSD1 can function as activators in AR-negative prostate cancer cell lines, indicating their potential involvement in an AR-independent complex." (PMID 37663929, 2023). "Silencing EHMT1 or EHMT2 effectively suppresses prostate cancer cell proliferation and migration." (PMID 37663929, 2023). "Given our recent findings of nuclear condensates between LSD1 and BRD4 driving super-enhancer activation in prostate cancer cells, it is plausible that EHMT1 may also participate in these complexes." (PMID 37663929, 2023). "In addition, the strong activity of EHMT1 in promoting prostate cancer metastasis suggests its potential involvement in regulating metastasis-related transcription factors, such as MYC." (PMID 37663929, 2023). "In this study, we demonstrate that EHMT1 and EHMT2 proteins drive prostate cancer development by transcriptionally activating multiple oncogenic pathways." (PMID 37663929, 2023). "Overall, these studies suggest a strong therapeutic potential for using dual inhibitors of EHMT1 and EHMT2 for treating prostate cancer." (PMID 37663929, 2023). "Another study proposes that EHMT1, along with other H3K9 methyltransferases, drives prostate cancer resistance to ADTs by enabling transcriptional silencing of retroelements." (PMID 37663929, 2023). "Through comprehensive investigations, we discovered that both EHMT1 and EHMT2 proteins have the ability to activate oncogenic transcription programs in prostate cancer cells." (PMID 37663929, 2023). "The rearrangements of UBAP2L and EHMT1 have been reported in liver, lung, breast, ovary, and prostate cancer but not in hematological malignancies, and ABL1 or BCR has not been reported as their partner genes." (PMID 39596557, 2024). "The inhibitor treatment suppressed the levels of H3K9me2 in prostate cancer cells but did not affect the protein expression of EHMT1." (PMID 37663929, 2023). "To determine the role of EHMT1 and EHMT2 in prostate cancer progression, we examined their protein levels in adenocarcinoma prostate cancer lines (LNCaP, 22Rv1) and stem cell or neuroendocrine (NE)-like prostate cancer lines (PC-3, NCI-H660)." (PMID 37663929, 2023).
schizophrenia (5 papers, 2014 to 2024). A major psychotic disorder characterized by abnormalities in the perception or expression of reality. "Analysis of the EHMT1-regulated miRNA expression profile, including miR-153, miR-26a and miR-142, indicates a broader association between EHMT1 regulated miRNA, NRSF/REST and both ID and schizophrenia." (PMID 36216811, 2022). "Given the potential association between EHMT1 activity and patient diagnosis that extends across a range of NDD, we examined the relationship between the up-regulated miRNA gene set due to reduced EHMT1 activity and GWAS data for ID, schizophrenia and ASD." (PMID 36216811, 2022). "A recent study showed increased expression of the EHMT2 gene in lymphocytes and the EHMT1 gene in both postmortem parietal cortex and lymphocyte samples, from patients with schizophrenia." (PMID 25400900, 2014).
breast carcinoma (4 papers, 2014 to 2026). "Although there was no significant change in the expression of PCAF and HLCS, the expression level of GCN5 was reduced, and EHMT-1 was increased in BRCA1-mutated breast cancer (P < 0.05)." (PMID 24675476, 2014). "Targets with the highest numbers of interactions with Chrysanthemum phytochemicals (degree = 6) including PGR, HEM6 and EHMT1 might be major therapeutic targets for breast cancer." (PMID 34083561, 2021).
Cognitive impairment (4 papers, 2022 to 2025). Abnormal cognition is characterized by deficits in thinking, reasoning, or remembering. "Therefore, it can be assumed that treating chromatin modifications regulated by euchromatin methyltransferases EHMT1/2 can effectively restore memory-related cognitive defects." (PMID 40890826, 2025). "By inhibiting EHMT1 and EHMT2, which catalyze H3K9me2, the recovery of synaptic function and transmission lost during the onset of Alzheimer’s was observed, together with an improvement of cognitive deficits in aged FAD mice." (PMID 40890826, 2025).
cardiac hypertrophy (3 papers, 2022 to 2024). "Conversely, Ehmt2 inhibits cell death of primary aortic vascular smooth muscle cells by suppressing autophagy, and research demonstrated miR-207 to repress Ehmt1 and Ehmt2 expression leading to cardiac hypertrophy." (PMID 39285385, 2024).
viral infection (3 papers, 2014 to 2024). "Intrigued by the altered localization of EHMT1 in response to viral infection, we continued our investigation to uncover the role of EHMT1 in Sendai viral life cycle." (PMID 39509467, 2024). "In other work, in viral infection SP1 regulates HIST1H1C which subsequently modulates EHMT1/EHMT2 complex formation and gene expression." (PMID 35139903, 2022). "We previously showed that inhibition of EHMT1 either with RNA interference (RNAi) or a chemical inhibitor enhances interferon response and protects cells from virus infection." (PMID 25079219, 2014). "Down-regulation of EHMT1 either upon infection or by addition of inhibitors has been reported to activate the Type 1 Interferon signalling pathway via ISGs and Ifit2, which imparts an antiviral response to the host by aiding in clearance of viral infection." (PMID 39509467, 2024). "Inhibition of EHMT2 by gene knockout in mice or inhibition of EHMT1 and EHMT2 with a chemical inhibitor, BIX01294, enhances type I interferon response and protect cells from viral infection." (PMID 25079219, 2014). "We found that EHMT1 localized to the IBs formed by N and P independent of viral infection." (PMID 39509467, 2024).
Alzheimer disease (2 papers, 2024). A progressive, neurodegenerative disease characterized by loss of function and death of nerve cells in several areas of the brain leading to loss of cognitive function such as memory and language. "In addition, the expression levels of EHMT1 in the prefrontal cortex correlate positively with the progression of Alzheimer’s disease (AD), and inhibition of EHMT1/2 rescues synaptic and cognitive functions in AD model mice." (PMID 38472451, 2024).
Arrhythmia (2 papers, 2023 to 2026). Any cardiac rhythm other than the normal sinus rhythm. "Further studies are needed to clarify the link between EHMT1 and cardiac arrhythmias and to establish the potential role of EHMT1 in the epigenetic modulation of cardiac pacemakers." (PMID 41654978, 2026).
congenital heart disease (2 papers, 2022 to 2023). A heart disease that is present at birth. "Mutations in histone modifiers KMT2D (histone-lysine N-methyltransferase 2D) and KDM6A (lysine-specific demethylase 6A) and EHMT1 (euchromatic histone-lysine N-methyltransferase 1) have also been associated with syndromic congenital heart disease due to defects in NCC development." (PMID 35108221, 2022).
gastric cancer (2 papers, 2020 to 2021). A primary or metastatic malignant neoplasm involving the stomach. "Clinicopathologic associations of EHMT1, a transcriptional repressor that functions via H3K9 methylation, have been reported in gastric cancer." (PMID 33050946, 2020). "EHMT1 was found to be significantly overexpressed in 97 gastric cancer tissues compared to their normal counterparts, and was associated with tumor stage and lymph node metastasis." (PMID 33050946, 2020). "While further investigations are warranted, these preliminary findings demonstrate that EHMT1 may play a significant role in gastric cancer pathogenesis." (PMID 33050946, 2020).
neuroblastoma (2 papers, 2021 to 2023). Neuroblastoma (NB) is the most common solid, extracranial childhood tumor. "Our results show that G9a/Ehmt2 and GLP/Ehmt1 expression is higher in tumors with poorer prognosis, including St4 International Neuroblastoma Staging System (INSS) stage, MYCN amplified NB, and metastatic ES." (PMID 37894922, 2023). "UNC0642, a well-known EHMT1/2 selective inhibitor, has been widely reported to inhibit the growth of multiple kinds of cancer cells including neuroblastoma, melanoma, bladder cancer, non-small cell lung cancer, etc.." (PMID 34344448, 2021).
ovarian carcinoma (2 papers, 2019 to 2023). A malignant neoplasm originating from the surface ovarian epithelium. "Further study is required to determine if EHMT1/2 interacts with MYC, or other pro-survival signaling pathways, in the context of PARPi-resistant ovarian cancer." (PMID 31775874, 2019).
aortic coarctation (1 paper, 2021). "In patients with EHMT1 mutation: TOF, ASD, VSD, aortic coarctation, bicuspid aortic valve, and pulmonic stenosis." (PMID 33968946, 2021).
B-cell acute lymphoblastic leukemia (1 paper, 2023). A neoplasm of lymphoblasts committed to the B-cell lineage, typically composed of small to medium-sized blast cells. "It was previously demonstrated that HP1γ functions as a coactivator of GR after its recruitment through the histone lysine methyltransferases G9a and GLP (EHMT2 and EHMT1, respectively) in lung adenocarcinoma and B-cell acute lymphoblastic leukemia." (PMID 37536978, 2023).
brachydactyly (1 paper, 2021). A disease characterized by the presence of brachydactyly, including syndromic and non-syndromic forms. "Of the genes associated with congenital abnormality, four genes (HDAC4, PTCH1, EHMT1, SYK) were associated with brachydactyly, according to the DisGeNET database." (PMID 34246298, 2021).
channelopathy (1 paper, 2023). Channelopathies are a group of diseases caused by the dysfunction of ion channel subunits or their interacting proteins. "It is possible that EHMT1 either directly (via a channelopathy) or indirectly (via its regulation of cardiac cellular maturation) modulates ion channels and gap junction function and expression." (PMID 38195854, 2023).
colorectal cancer (1 paper, 2022). A primary or metastatic malignant neoplasm that affects the colon or rectum. "Inhibition of the euchromatic histone lysine methyltransferases 1 and 2 (EHMT1/2) enhanced the antiproliferative activity of HDAC inhibitors in colorectal cancer and reduced H3K9 methylation." (PMID 36300880, 2022).
deafness (1 paper, 2016). An inherited or acquired condition characterized by the complete loss of the ability to hear from one or both ears. "Apart from EHMT1, the other six are associated with congenital lipodystrophy type 1, mental retardation, deafness, hypophosphatemic rickets, and hypogonadotropic hypogonadism." (PMID 27239352, 2016).
dementia (1 paper, 2023). Loss of intellectual abilities interfering with an individual's social and occupational functions. "However, only six of these genes emerged to be associated with AD in a certain way: HMGB1, which is related AD dementia according to ‘Disease Ontology’; KANSL1; BAZ2B; EHMT1; SIRT1; and CTBP1, which are associated with AD according to the literature data." (PMID 37175659, 2023).
esophageal squamous cell carcinoma (1 paper, 2021). Esophageal squamous cell carcinoma (ESCC) is a type of esophageal carcinoma (EC) that can affect any part of the esophagus, but is usually located in the upper or middle third. "When complexed with G9a, EHMT1 is mainly responsible for monomethylation‐ and dimethylation‐related modifications of H3K9 in euchromatin regions, and EHMT1 overexpression is associated with poor cancer‐specific survival in esophageal squamous cell cancer." (PMID 34214254, 2021).
glaucoma (1 paper, 2022). Increased pressure in the eyeball due to obstruction of the outflow of aqueous humor. "Twelve of these genes, including PTPRB, HFM1, TAF1B, AAK1, FOXD1, EHMT1, and DNTT, are associated with glaucoma topical treatments (P < 1 × 10−5)." (PMID 36450729, 2022).